KIAA1549 (KIAA1549)
Diseases named in the same sentence as KIAA1549 in open-access papers (continued):
Sharing a sentence is not in itself a finding about the gene and the disease.
pilocytic astrocytoma (continued). "Of those recurrently affected boundaries, two adjacent boundaries between KIAA1549 and BRAF were prone to BA-duplications specifically in samples of pilocytic astrocytoma." (PMID 32024999, 2020). "KIAA1549-BRAF is the most frequent molecular alteration in pLGG, and is significantly enriched in pilocytic astrocytoma and in tumors arising in the posterior fossa/cerebellum." (PMID 32164789, 2020). "These include KIAA1549-BRAF, typically resulting from tandem duplication and characteristic of pilocytic astrocytoma, C11orf95-RELA in supratentorial ependymoma, and FGFR-TACC (e.g. FGFR3-TACC3) in a subset of infiltrating gliomas, among others." (PMID 32493417, 2020). "Some of these tumors have BRAF duplications and KIAA1549-BRAF fusions, suggesting that a minority of these tumors share a common molecular background with classical pilocytic astrocytomas." (PMID 31181803, 2019). "• KIAA1549-BRAF fusion, a recurrent oncogenic driver in sporadic pilocytic astrocytoma, is described here in a spindle cell neoplasm for the first time." (PMID 24422672, 2014). "Although many other gene fusions, involving several genes, have been described as critical driver events in pediatric LGG, the KIAA1549-BRAF fusion is one prominent molecular marker, most frequently detected and assists in the diagnosis of pilocytic astrocytoma." (PMID 35363819, 2022). "The absence of KIAA1549-BRAF fusion did not necessarily exclude the diagnosis of a pilocytic astrocytoma." (PMID 32758285, 2020). "Rare cases of pediatric oligodendrogliomas display the KIAA1549-BRAF fusion with activation of the MAPK/ERK pathway: these rare tumors represent a subset of pediatric oligodendrogliomas with molecular and genetic features of pilocytic astrocytomas." (PMID 30279357, 2018). "Morphologically, the glial component of both tumors are identical, and could explain the finding of KIAA1549:BRAF fusion, that is frequently found in pilocytic astrocytomas." (PMID 26371886, 2015). "The KIAA1549-BRAF fusion typically observed in pilocytic astrocytoma is absent in PXA." (PMID 30279357, 2018). "Notably, none of the tumors in our sample cohort harbored KIAA1549-BRAF fusions, which are commonly associated with pilocytic astrocytomas and were recently reported in a small set of two neoplasms classified as “pediatric oligodendrogliomas”." (PMID 27812792, 2017). "This included the majority of the pilocytic astrocytomas, which often lacked the prototypical Rosenthal fibers, piloid processes, and biphasic pattern with alternating loose and compact growth that is characteristic of pilocytic astrocytomas with KIAA1549-BRAF fusion." (PMID 32859279, 2020). "Using these parameters, we observed a copy number gain > 2.25 in all 13 cases with KIAA1549-BRAF fusions and in one pilocytic astrocytoma lacking detectable KIAA1549-BRAF fusions by RT-PCR analysis." (PMID 35361262, 2022). "Additionally, KIAA1549-BRAF and C11orf95-RELA were found in cases of pilocytic astrocytoma and subependymoma, respectively (data not shown)." (PMID 38363490, 2024). "In this patient cohort, there were 18 patients confirmed negative for the KIAA1549–BRAF fusion including the diagnoses: glioneuronal tumor, astrocytoma NOS, pilocytic astrocytoma, gemistocitic astrocytoma, ganglioglioma, and LGG with pilocytic/pilomyxoid features." (PMID 33063010, 2020).
glioma (34 papers, 2013 to 2026). A benign or malignant brain and spinal cord tumor that arises from glial cells (astrocytes, oligodendrocytes, ependymal cells). "Studies in mice indicate that while a KIAA1549::BRAF fusion is sufficient to generate glioma-like lesions, this is associated with increased Iba1+ microglia infiltration and is inhibited if Ccr2-mediated microglial recruitment is blocked." (PMID 39948623, 2025). "A phase II study to confirm the efficacy and safety of trametinib as single agent in NF1-associated LGG and non-NF1 gliomas with either KIAA1549-BRAF fusion or activation of the MAPK/ERK pathway, is ongoing (NCT03363217)." (PMID 35784925, 2022). "A clinical trial evaluating safety and efficacy of the MEK1/2 inhibitor, binimetinib, is underway in children with glioma and other tumors containing KIAA1549–BRAF fusions or other activating mutations with some early signals of efficacy." (PMID 31466300, 2019). "In sporadic low-grade gliomas driven by KIAA1549:BRAF and familial low-grade gliomas associated with protein neurofibromin 1 (NF1), mTOR represents a central growth control target." (PMID 23717811, 2013). "For that purpose, we analyzed two more pediatric glioma tissues, one additional PA (ICGC_PA74, KIAA1549::BRAF fusion) and one pleomorphic xanthoastrocytoma (PXA, a CNS WHO grade 2–3 tumor, I007_024, BRAF V600E and CDK2 NA/B deletion)." (PMID 40229354, 2025). "In pediatric gliomas, specific genetic alterations are more commonly seen, such as BRAF fusion or mutation, KIAA1549-BRAF fusion, and mutations in histone genes (H3F3A or HIST1H3B)." (PMID 37444408, 2023). "Pediatric gliomas, on the other hand, are frequently associated with genetic alterations such as BRAF fusion or mutation, KIAA1549-BRAF fusion, and mutations in H3F3A or HIST1H3B." (PMID 37444408, 2023). "The most common non-FGFR1 alterations were IDH1/2 mutations (234 cases), KIAA1549-BRAF fusion (73 cases), 24 TERT C228/C250-mutated gliomas and 35 cases with NF1." (PMID 35018490, 2022). "For lowly expressed gene fusions such as KIAA1549-BRAF in low grade glioma, the sensitivity of detection is low for both CICERO as well as the other commonly used fusion detection methods tested here." (PMID 32466770, 2020). "In the current study we examine the prevalence of KIAA1549-BRAF gene fusion in pediatric patients diagnosed with low grade glioma in the Egyptian population and its relationship to clinical and histological subtypes." (PMID 25883769, 2015). "It is interesting to note that in contrast to glioma, KIAA1549-BRAF is the most common BRAF fusion." (PMID 36612279, 2022). "Examination of the gene-targeted “Clinical Glioma” and “KIAA1549-BRAF fusion” panels revealed that 98.2% (112/114) of brain astrocytomas had at least one molecular alteration (mutation or fusion), while only 65% (36/55) of IMAs had at least one alteration (Fisher test: p < 10− 6)." (PMID 32771057, 2020). "In contrast, KIAA1549:BRAF fusion variants are rare in these tumors, being observed only in low-grade glioneuronal (gangliogliomas) tumors (36%) and low-grade unclassifiable gliomas (17%)." (PMID 30279357, 2018). "KIAA1549-BRAF fusions have previously been shown to be associated with better patient survival while BRAFV600E has been linked to increased likelihood of tumour progression and transformation in low grade glioma." (PMID 27577993, 2016). "In addition to H3K27M, genetic aberrations affecting the RAS-MAPK pathway including KIAA1549-BRAF and other BRAF, RAF and FGFR fusion events, as well as BRAF and FGFR1 point mutations have been described primarily in hemispheric low grade gliomas in adults and children." (PMID 27577993, 2016).
glioma (continued). "Tovorafenib has recently received approval for treatment of pediatric low-grade gliomas driven by KIAA1549:BRAF, a constitutively dimerized form of BRAF created by its truncation and fusion with a portion of the KIAA1549 ORF." (PMID 41072765, 2025). "For example, the MEK inhibitor selumetinib demonstrated activity in BRAF V600E-mutant, KIAA1549:BRAF fusion positive and NF1-mutant (lower grade) gliomas, providing a rationale for its evaluation in HGAP." (PMID 33905054, 2021). "The BRAF V600E mutation, among other molecular aberrations of this gene (in particular the presence of KIAA1549-BRAF fusions), is found in several CNS tumors, including gliomas and glioneuronal tumors." (PMID 32879641, 2020). "The most common fusion is KIAA1549–BRAF, which was first identified in low-grade glioma and is composed of the N-terminal dimerization domain of KIAA and the C-terminal kinase domain of BRAF." (PMID 31466300, 2019). "While KIAA1549::BRAF remains the most prevalent fusion, an expanding repertoire of alternative fusion partners continues to refine the molecular landscape of MAPK-driven gliomas and has important therapeutic implications." (PMID 41659712, 2026). "Pediatric gliomas often harbor BRAF fusions (e.g., KIAA1549-BRAF) that also respond to dabrafenib, though the drug’s efficacy may vary depending on the specific mutation type and tumor microenvironment." (PMID 39654184, 2024). "In terms of prognosis, the KIAA1549 BRAF fusion has been described as an independent positive prognostic biomarker in low-grade pediatric gliomas, irrespective of tumor type." (PMID 25785246, 2015). "In certain studies, the KIAA1549:BRAF fusion gene was also found to function through MEK-dependent activation of both MAPK and mTOR pathways and the injection of neural stem cells containing the fusion were sufficient to induce glioma-like lesions in mice." (PMID 25785246, 2015). "For example, while KIAA1549-BRAF and BRAFV600E mutations have shown to correlate with better outcomes in pediatric intramedullary low-grade gliomas, their impact on adult intramedullary gliomas is not clear." (PMID 38254893, 2024).
astrocytomas (17 papers, 2013 to 2025). "The few available studies specific to the molecular alterations of intramedullary astrocytomas (IMAs) have been performed and have shown that the most frequent recurrent molecular alterations are fusions involving KIAA1549-BRAF and H3K27M mutations." (PMID 32771057, 2020). "In preclinical studies, PLX7904 and its optimised analogue PLX8394 had activity in vemurafenib-resistant melanoma lines expressing dimeric V600E-B-Raf splice variants and in paediatric astrocytomas expressing dimeric KIAA1549:B-Raf fusion proteins." (PMID 29235562, 2018). "BRAF mutations, such as KIAA1549: BRAF and BRAF V600E have been linked to the progression of astrocytoma, according to our investigation." (PMID 37675821, 2023). "In sporadic circumscribed astrocytoma, KIAA1549‐BRAF is a documented hereditary change resulting in the combination of BRAF protein (f‐BRAF) and increased BRAF mobility." (PMID 37675821, 2023). "Recent breakthrough studies found that BRAF mutations, including KIAA1549: BRAF and BRAF V600E are responsible for astrocytoma progression." (PMID 37675821, 2023). "Of note, the frequency of fusion breakpoint location differ between intracranial and intramedullary astrocytomas harboring a KIAA1549-BRAF fusion." (PMID 36147920, 2022). "Important differences in the frequency and types of mutations have been noted across the two regions—for example, although KIAA1549-BRAF fusions are detected in astrocytomas in both regions, their frequency and breakpoint locations have been noted to differ." (PMID 36147920, 2022). "One case (KIAA1549:BRAF ex10:ex9) was classified as desmoplastic infantile ganglioglioma / desmoplastic infantile astrocytoma (CS 0.59)." (PMID 36163281, 2022). "A study of 17 spinal cord astocytomas revealed that 80% of grade I astrocytomas harbored mutations in the BRAF genes, with 40% harboring BRAF-KIAA1549 translocation and the other 60% harboring a BRAF copy number gain." (PMID 34685506, 2021). "In animal studies, MLN2480/TAK-580 exhibited good brain and tumour penetrance, a property that will be needed to suppress the activity of KIAA1549:B-Raf fusion proteins found in 75% of paediatric low-grade astrocytomas." (PMID 29235562, 2018). "This correlates with our previous study where combination of everolimus with selumetinib was found efficacious in targeting the BT-40 (BRAF-V600E) astrocytoma cell line as well as NIH3T3 expressing KIAA1549-BRAF." (PMID 29156677, 2017). "The gene fusions, identified by ADx in samples lacking FISH confirmation (sample 41–52), were in line with the patient’s diagnosis: KIAA1549-BRAF in astrocytoma, ALK or NTRK translocations in thyroid papillary carcinoma, lung adenocarcinoma as well as sarcomas NOS." (PMID 36338518, 2022). "Unlike KIAA1549-BRAF fusion transcripts which were near exclusively expressed in grade I astrocytomas, BRAF V600E mutation was detected in 22.6% of grade II-IV tumors but in none of the grade I tumors." (PMID 29152094, 2017). "Fusions involving the BRAF and KIAA1549 genes are found in nearly 80% of cerebellar grade I astrocytomas but only 50–55% of non-cerebellar grade I cases." (PMID 32771057, 2020). "However, this case already indicates such treatment possibilities exist for patients possessing KIAA1549-BRAF fusions, whether in pediatric astrocytomas or difficult to characterize sarcoma like lesions." (PMID 24422672, 2014).
ganglioglioma (14 papers, 2014 to 2025). A well differentiated, slow growing neuroepithelial neoplasm composed of neoplastic, mature ganglion cells and neoplastic glial cells. "The two thalamic gangliogliomas both harbored BRAF p.V600E mutation, three of the four cerebellar gangliogliomas harbored BRAF p.V600E mutation, and two of three gangliogliomas centered in the spinal cord harbored KIAA1549-BRAF fusion." (PMID 29880043, 2018). "Recent studies on the gangliogliomas of the CNS also identified rare cases of gangliogliomas with a pilocytic component having the identical KIAA1549-BRAF fusion gene as those of PAs (Melike Pekmezci, personal communication)." (PMID 29983406, 2019). "The two gangliogliomas in our cohort with KIAA1549-BRAF fusion were both located in the spinal cord of children and demonstrated numerous dysmorphic ganglion cells throughout the entirety of the tumor, indicating that classic gangliogliomas can also harbor KIAA1549-BRAF fusion." (PMID 29880043, 2018). "However, such genetic abnormalities were not harbored by those gangliogliomas in which we were unable to show a KIAA1549-BRAF fusion or BRAF:p.V600E mutation." (PMID 24529209, 2014). "For example, BRAF p.V600E has been observed in 25%–35% of adult and pediatric gangliogliomas, whereas other BRAF genetic alterations and KIAA1549-BRAF and FAM131B-BRAF fusions have also been observed in low-grade gliomas, the former fusion having been identified in gangliogliomas." (PMID 29434027, 2018). "Therefore, the frequency of KIAA1549-BRAF fusions in infratentorial PAs and gangliogliomas appears very similar." (PMID 24529209, 2014). "On the other hand, all 9 gangliogliomas and the remaining 25 LGG cases were negative for the KIAA1549-BRAF fusion." (PMID 35363819, 2022).
low grade glioma (11 papers, 2017 to 2024). A grade I or grade II glioma arising from the central nervous system. "Previous studies found that BRAF mutations as well as KIAA1549–BRAF fusions are common in intracranial low-grade gliomas (LGGs)." (PMID 33063010, 2020). "We aimed to develop machine learning models for prediction of molecular subgroups (low-risk group and intermediate/high-risk group) and molecular marker (KIAA1549-BRAF fusion) of pediatric low-grade gliomas (PLGGs) based on radiomic features extracted from multiparametric MRI." (PMID 37697238, 2023). "BRAF is a known oncogene that activates the RAS-MAPK signaling pathways, and has been described with numerous fusion partners, including the common KIAA1549-BRAF fusion in pediatric low-grade gliomas." (PMID 34863095, 2021). "We also identified recurrent KIAA1549/BRAF fusions in Pilomyxoid astrocytoma tumors which is an emerging diagnostic and prognostic marker in pediatric low-grade gliomas that predicts positive response to certain MEK inhibitors." (PMID 33889297, 2021). "Pediatric low-grade gliomas (PLGGs) are frequently associated with activating BRAF gene fusions, such as KIAA1549-BRAF, that aberrantly drive the mitogen activated protein kinase (MAPK) pathway." (PMID 29156677, 2017). "Pediatric low-grade glioma (pLGG) is essentially a single pathway disease, with most tumors driven by genomic alterations affecting the mitogen-activated protein kinase/ERK (MAPK) pathway, predominantly KIAA1549::BRAF fusions and BRAF V600E mutations." (PMID 38291372, 2024).
brain tumors (8 papers, 2018 to 2023). "This includes KIAA1549 and CALD1, which are associated with brain tumors and regulation of muscle contraction, respectively." (PMID 37664632, 2023). "Previous pioneering array studies, mostly done on PA tumors, indicated involvement of KIAA1549-BRAF fusion gene in low-grade brain tumors." (PMID 36860324, 2023). "BRAF mutations, particularly the V600E mutation and KIAA1549-BRAF fusions, are also present in a significant subset of primary brain tumors." (PMID 35155453, 2021). "Here we examine single cell transcriptional profiles of pediatric low-grade brain tumors using a workflow developed specifically to detect KIAA1549-BRAF rearranged PA cells." (PMID 31427603, 2019). "BRAF mutations, particularly the V600E mutation and KIAA1549–BRAF fusions, are present in a significant subset of primary brain tumors." (PMID 31466300, 2019). "A further tumor harbored the KIAA1549-BRAF fusion, a molecular hallmark of a childhood brain tumor, pilocytic astrocytoma." (PMID 29915264, 2018). "In addition to being potent against KIAA1549:BRAF, tovorafenib is brain-penetrant, and as such, it is being evaluated in PLGA, a brain tumor that is frequently driven by the KIAA1549:BRAF fusion." (PMID 36963492, 2023).
glioneuronal tumor (5 papers, 2019 to 2024). "The rare KIAA1549:BRAF ex13:ex11 fusion variant was only described in one case of spinal glioneuronal tumor." (PMID 36163281, 2022).
pilomyxoid astrocytoma (5 papers, 2014 to 2025). An astrocytic tumor of uncertain relation to pilocytic astrocytoma. "While the BRAF V600E mutation is found in about 60% of pleomorphic xanthoastrocytoma (PXA), 50% of gangliomas, 9% of PA and 2–12% glioblastoma, the KIAA1549–BRAF fusion is frequently found roughly in 50–80% of PA and pilomyxoid astrocytomas (PMA), which is an aggressive variant of PA." (PMID 35363819, 2022). "KIAA1549-BRAF fusion was present in 9 of 15 samples analysed for this fusion: 8 samples were a PA and 1 a pilomyxoid astrocytoma." (PMID 36551572, 2022). "All KIAA1549::BRAF fusion-positive LGGs were confirmed to have a PA (N = 158), pilomyxoid astrocytoma (PMA, N = 9), mixed pilocytic/pilomyxoid astrocytoma (N = 2), or fibrillary astrocytoma (N = 3) diagnosis." (PMID 39847453, 2025).
diffuse leptomeningeal glioneuronal tumor (4 papers, 2018 to 2025). A central nervous system benign neoplasm that is characterized by the presence of clear glial neoplastic cells reminiscent of oligodendroglioma. "Another recently described tumor entity is diffuse leptomeningeal glioneuronal tumor (also referred to as disseminated oligodendroglioma-like leptomeningeal neoplasm), which is genetically characterized by the combination of monosomy 1p and KIAA1549-BRAF fusion." (PMID 29880043, 2018).
glioblastoma (4 papers, 2020 to 2023). The most malignant astrocytic tumor (WHO grade IV). "Of the cases lacking KIAA1549-BRAF fusions, a patient harboring a GOPC-ROS1 fusion of was of interest, as this alteration has been previously reported in an undefined glioblastoma patient." (PMID 31995621, 2020).